CNNM2 (cyclin and CBS domain divalent metal cation transport mediator 2)
Description:
Divalent metal cation transporter. Mediates transport of divalent metal cations in an order of Mg(2+) > Co(2+) > Mn(2+) > Sr(2+) > Ba(2+) > Cu(2+) > Fe(2+) (By similarity).
Synonyms: ACDP2; SLC70A2; HOMG6; HOMGSMR
Tractability: Small molecule: a structure with a bound ligand is known. Antibody: UniProt places it where antibodies can reach, with medium confidence; UniProt predicts a signal peptide or a membrane-spanning region; its Gene Ontology location is reachable by antibodies, with medium confidence. PROTAC: ubiquitination databases record sites on it; its protein half-life has been measured.
Gene: Protein-coding gene on chromosome 10 (102,918,286 to 103,090,222, forward strand). Ensembl gene ENSG00000148842.
Subcellular location: Cell membrane
Subcellular location (Human Protein Atlas): Vesicles
Gene Ontology:
Molecular function: magnesium ion transmembrane transporter activity; ATP binding
Biological process: magnesium ion homeostasis; magnesium ion transmembrane transport
Cellular component: basolateral plasma membrane; plasma membrane; glutamatergic synapse; synapse
Genetic constraint (gnomAD): Loss-of-function variants: 12 observed, 62.4 expected, observed/expected ratio (o/e) 0.19, 90% interval 0.12 to 0.31. The upper end of that interval is the gene's LOEUF score, 0.31, which puts it in group 1 of 6, group 1 being the genes least tolerant of losing a copy. Missense variants: 705 observed, 1,176.1 expected, observed/expected ratio (o/e) 0.6, 90% interval 0.56 to 0.64. Synonymous variants: 557 observed, 502.68 expected, observed/expected ratio (o/e) 1.11, 90% interval 1.03 to 1.19.
Gene-disease validity (ClinGen):
ClinGen rates the evidence that CNNM2 causes each of these diseases.
hypomagnesemia, seizures, and intellectual disability 1 (semidominant): Definitive.
Homologues: Orthologues: chimpanzee CNNM2 (100% identical), dog CNNM2 (99% identical), pig CNNM2 (99% identical), mouse Cnnm2 (98% identical), macaque CNNM2 (93% identical), rabbit CNNM2 (91% identical), rat Cnnm2 (89% identical), tropical clawed frog cnnm2 (82% identical), zebrafish cnnm2a (74% identical), zebrafish cnnm2b (73% identical), guinea pig CNNM2 (54% identical), Drosophila melanogaster uex (39% identical), and 3 more. Paralogues in human: CNNM4 (56% identical), CNNM1 (48% identical), CNNM3 (36% identical).
Diseases named in the same sentence as CNNM2 in open-access papers:
CNNM2 is named in the same sentence as 61 diseases in open-access papers, as found by Europe PMC text mining. Sharing a sentence is not in itself a finding about the gene and the disease. The quoted sentences say what the papers report.
Hypomagnesemia (25 papers, 2014 to 2025). An abnormally decreased magnesium concentration in the blood. "Pathogenic mutations in CNNM2 have been linked to hypomagnesemia, intellectual disabilities, and epilepsy." (PMID 40003994, 2025). "Subsequently, identified heterozygous or homozygous CNNM2 mutations in patients with NDDs, revealing a connection between CNNM2 gene mutations and hypomagnesemia, seizures, and impaired intellectual development 1 (HOMGSMR1, OMIM #616418)." (PMID 40612795, 2025). "The flat orientation of the CBS domain orientation is thought to inhibit magnesium export, as mutations associated with hypomagnesemia in CNNM2 similarly lock the structure in a flat conformation, impairing magnesium extrusion." (PMID 40003994, 2025). "Deficiency of the divalent cation metal transporter CNNM2 has been causally associated with hypomagnesemia and BP deregulation." (PMID 38326862, 2024). "Beyond hypomagnesemia, CNNM2 variants display various clinical manifestations from the central nervous system (CNS) ranging from headache to epileptic seizures, mental retardation, and structural malformations of the brain tissue." (PMID 35806288, 2022). "Here, we report a family with a novel CNNM2 p.Pro482Ala variant, presenting with overt hypomagnesemia and mild neurological involvement (autosomal dominant renal hypomagnesemia 6, HOMG6, MIM# 613882)." (PMID 35806288, 2022). "Renal hypomagnesemia syndromes involving CNNM2 protein pathogenic variants are associated with variable degrees of neurocognitive dysfunction and hypomagnesemia." (PMID 35806288, 2022). "Herein, we present a novel CNNM2 variant associated with severe hypomagnesemia and mild neurological phenotype (HOMG6) in a Greek family and discuss our therapeutic approach with spironolactone to restore normal serum magnesium levels." (PMID 35806288, 2022). "Mutations in CNNM2 have been reported to cause hypomagnesemia, seizure, and intellectual disability (HSMR) syndrome." (PMID 35846113, 2022). "Homozygous and heterozygous variants in CNNM2 reported so far were responsible for a variable degree of hypomagnesemia, several of which also showed varying degrees of neurological phenotypes such as intellectual disability and epilepsy." (PMID 34490037, 2021). "Cnnm2 is a vital candidate gene related to magnesium ion (Mg2+) balance, which is mutated in dominant hypomagnesemia." (PMID 34220431, 2021). "Type 2, AD-inherited hypomagnesemia with epilepsy and ID/DD, is the most common phenotype in cases with CNNM2 variant (15/23)." (PMID 34604137, 2021). "Mutations in CNNM2 gene are implicated in mental retardation and seizures in patients with hypomagnesemia." (PMID 34899152, 2021). "Thereafter, in HEK293 cell line-based experiments, it was found that the influx of sodium ions was decreased in cells transfected with the CNNM2 p.Thr568Ile mutation (a mutation causing hereditary hypomagnesemia) compared with wild type." (PMID 34604137, 2021). "A search for hypomagnesemia will be made in the patient with the variant in CNNM2, as this too is treatable." (PMID 33912281, 2021). "In humans, point mutations in CNNM2 cause hypomagnesemia, while mutations in CNNM4 are associated with Jalili syndrome." (PMID 34766907, 2021). "CNNM2 (Cystathionine-β-synthase-pair Domain Divalent Metal Cation Transport Mediator 2) pathogenic variants have been reported to cause hypomagnesemia, epilepsy, and intellectual disability/developmental delay (ID/DD)." (PMID 34604137, 2021). "So far, according to the Human Gene Mutation Database, 6 pathogenic variants in the CNNM2 gene associated with hypomagnesemia or with hypomagnesemia, seizures, and mental retardation have been described." (PMID 32997713, 2020). "Several point mutations in CNNM2 have been identified in human patients with hypomagnesemia, which is associated with brain malformation and intellectual disability." (PMID 33242000, 2020).
Hypomagnesemia (continued). "Normally, Mg2+ is not requested in a routine blood test, therefore after the discovery of the variants in the CNNM2 gene (gene associated with dominant hypomagnesemia) a new blood test was requested." (PMID 32997713, 2020). "In an apparent contradiction, the mutation of residue T568I, found in the CNNM2 protein of patients suffering familial hypomagnesemia, mimics the effect of the nucleotide in the Bateman module, despite this amino acid substitution impairing ATP binding." (PMID 30845649, 2019). "Loss of function mutations in CNNM2 has recently been reported to be causal of hypomagnesemia, seizures, and mental retardation." (PMID 29391398, 2018). "In line with the symptom of hypomagnesemia in patients with mutated CNNM2, cnnm2a morphants exhibited significantly reduced levels of Mg compared to controls when increasing doses of MO were injected." (PMID 24699222, 2014). "Accordingly, the extent of hypomagnesemia found in the two siblings with the recessive mutation, F1.1 and F1.2, was identical to other patients (F2.1–F5.1) with heterozygous CNNM2 mutations and a milder neurological phenotype." (PMID 24699222, 2014). "Recently, we have identified mutations in the gene encoding cyclin M2 (CNNM2) in two unrelated families with dominant isolated hypomagnesemia (CNNM2 [MIM 607803])." (PMID 24699222, 2014). "In this study, we have identified new mutations in CNNM2 in five families suffering from mental retardation, seizures, and hypomagnesemia." (PMID 24699222, 2014). "This defective Mg2+ efflux might account for the hypomagnesemia in this patient with CNNM2 R480L mutation." (PMID 35846113, 2022). "All patients who carried pathogenic variants in CNNM2 had hypomagnesemia." (PMID 34604137, 2021). "The phenotype of AR-inherited hypomagnesemia with epilepsy and ID/DD was more severe than that of AD-inherited, which suggests that the causative variant of CNNM2 may be loss of function (LOF)." (PMID 34604137, 2021). "Interestingly, a mutation in the Bateman module of CNNM2 was reported to cause a dominant form of blood hypomagnesemia, confirming the importance of this CNNM region in the regulation of magnesium homeostasis." (PMID 26969161, 2016). "Interestingly, the 2xCBS T436I mutation corresponding to the T568I mutation in CNNM2, shown to cause hypomagnesemia in human, also reduced PRL-2 binding." (PMID 26969161, 2016). "Currently, seven families with CNNM2 mutations suffering from hypomagnesemia have been described." (PMID 26969161, 2016). "Hence, we can demonstrate the genetic origin of symptoms in five unrelated families suffering from a distinct phenotype of mental retardation, seizures and hypomagnesemia, where we have identified novel mutations in the CNNM2 gene." (PMID 24699222, 2014). "Several forms of hereditary hypomagnesemia in humans have led to the identification of causative genes, including the transient receptor potential melastatin 6 (TRPM6) and cyclin M2 (CNNM2)." (PMID 35216094, 2022). "The role of CNNM2 in the kidney has been substantiated by studies of kidney-specific knockout mice of Cnnm2 which suffer from hypomagnesemia, demonstrating that CNNM2 regulates renal Mg2+ handling." (PMID 33859252, 2021). "This information on CNNM2 as Mg transporter has been validated in animal models in which CNNM2 knockout mice present hypomagnesemia and reduced kidney Mg reabsorption." (PMID 33282857, 2020). "In this study, we identify mutations in the gene encoding for cyclin M2 (CNNM2) to be causative for mental retardation and seizures in patients with hypomagnesemia." (PMID 24699222, 2014). "Hypomagnesemia, seizures, and impaired intellectual development 1 (HOMGSMR1) is a rare neurodevelopmental disorder associated with magnesium homeostasis disruption, caused by mutations in the CNNM2 gene." (PMID 40612795, 2025).
Hypomagnesemia (continued). "This highly expressed CNNM2-R480L properly localizes to the plasma membrane but impairs Mg2+ efflux likely through the attenuated interaction with Mg2+-ATP, resulting in the clinical manifestation of refractory hypomagnesemia." (PMID 35846113, 2022). "Although all patients with CNNM2-related disorders had hypomagnesemia, the serum magnesium was different in each case, which may be related to the protein domain where the variant was located." (PMID 34604137, 2021). "In agreement with this hypothesis, the CNNM2 T568I mutation (known to permanently lock the CBS module in the flat conformation) impairs the basolateral extrusion of Mg2+ at the renal DCT, thus causing hypomagnesemia." (PMID 30845649, 2019).
schizophrenia (15 papers, 2013 to 2025). A major psychotic disorder characterized by abnormalities in the perception or expression of reality. "NT5C2 and CNNM2 are involved in etiology and pathogenesis of schizophrenia and have been confirmed as schizophrenia susceptibility genes." (PMID 34899152, 2021). "The top-ranked susceptibility gene ATP5MD, encoding an ATP synthase membrane subunit, is observed to be downregulated in schizophrenia by the risk allele of CNNM2-rs1926032 in the schizophrenia-associated 10q24.32 locus." (PMID 34021155, 2021). "The PGC schizophrenia GWA study implicated CNNM2 among Caucasians and our current findings echoed this association in Asians." (PMID 31455759, 2019). "Among these five novel schizophrenia risk genes, we focused on Cnnm2, Csmd1, and Mmp16 in this study." (PMID 29163023, 2017). "Here, we examined alteration in the novel schizophrenia risk genes, CNNM2, CSMD1, and MMP16 in the brains of rats undergoing cesarean section with or without global hypoxia." (PMID 29163023, 2017). "Further study is needed to understand the underlying molecular mechanisms of CNNM2 in the brain development and the pathophysiology of schizophrenia." (PMID 29163023, 2017). "Here, we investigated the schizophrenia risk genes, CNNM2, CSMD1, and MMP16 (Schizophrenia Psychiatric Genome-Wide Association Study [GWAS] Consortium, 2011), and identified alterations in gene expression in the asphyxia rat model for schizophrenia." (PMID 29163023, 2017). "Further research will be needed to clarify the function of the risk CNNM2 variant on the pathophysiology of schizophrenia." (PMID 24160291, 2013). "In particular, the risk allele of CNNM2-rs1926032 (C/T) association with schizophrenia from PGC, Chinese Han, and CLOZUK GWAS data, was correlated with the downregulation of ATP5MD expression in human DLPFC brain tissues of the LFuN and LIBD eQTL datasets and luciferase reporter gene." (PMID 34021155, 2021). "Altogether, these results suggested that impaired ATP production and neurodevelopment induced by CNNM2-rs1926032 genotype-dependent ATP5MD downregulation might increase susceptibility to schizophrenia." (PMID 34021155, 2021). "Intriguingly, in line with our findings, it has been reported that a CNNM2 variant (Schizophrenia Psychiatric Genome-Wide Association Study [GWAS] Consortium, 2011) is associated with gray matter morphological vulnerability of the bilateral inferior frontal gyri." (PMID 29163023, 2017). "We suggest that the CNNM2 variant may play a role in the social cognition and social functioning impairments noted in patients with schizophrenia through GM volumetric vulnerability of the orbital regions of the inferior frontal gyri." (PMID 24160291, 2013). "It is still unclear whether and to what extent the effects of CNNM2 polymorphism on GM structure observed here might be associated with an increased risk for schizophrenia." (PMID 24160291, 2013). "Our findings suggest that the genetic variant in the CNNM2 gene could be implicated in the pathogenesis of schizophrenia through the GM volumetric vulnerability of the orbital regions in the inferior frontal gyri." (PMID 24160291, 2013). "Because, risk variants of CNNM2, CSMD1, and MMP16 are suggested to be involved in one of symptoms of schizophrenia, cognitive impairment." (PMID 29163023, 2017). "However, little is known about expression levels of CNNM2 in the brain of schizophrenia patients compared with control subjects." (PMID 29163023, 2017). "No allelic expression imbalance of CNNM2 associated with heterozygosity for the assayed schizophrenia risk variants survived Bonferroni correction." (PMID 27004590, 2016). "Although the role of CNNM2 beyond the kidney has never been studied, genome wide association studies have related the CNNM2 locus to blood pressure, coronary artery disease and schizophrenia, suggesting an important role of CNNM2 in the cardiovascular system and brain." (PMID 24699222, 2014).
schizophrenia (continued). "Unfortunately, in our sample sizes, there was no allelic association with schizophrenia for any of the five SNPs [rs7914558 (CNNM2), rs10503253 (CSMD1), rs7004633 (MMP16), rs11191580 (NT5C2) and rs12966547 (CCDC68)] (p > 0.22)." (PMID 24160291, 2013). "A meta-analysis of 18 GWASs for schizophrenia supported involvement of the MHC region, TCF4, POM121L2, NOTCH4, AS3MT, CNNM2, and NT5C2." (PMID 27064909, 2016). "Combined data from five Asian schizophrenia GWA studies (14, 433 cases and 26, 797 controls) and applicable Asian candidate-gene studies revealed two Bonferroni-significant LD-independent loci (CNNM2, MPC2) not identified in our candidate gene only meta-analyses." (PMID 31455759, 2019).
Intellectual disability (10 papers, 2014 to 2024). "Variants in the CNNM2 gene are causative for hypomagnesaemia, seizures and intellectual disability, although the phenotypes can be variable." (PMID 38519529, 2024). "Subsequently, epilepsy and intellectual disability/developmental delay (ID/DD) had been added to the spectrum of phenotypes of CNNM2 variants." (PMID 34604137, 2021). "Patients with mutations in Cyclin M2 (CNNM2) suffer from hypomagnesaemia, seizures, and intellectual disability." (PMID 33859252, 2021). "Nevertheless, a mild degree of intellectual disability has been described in other patients with variants in the CNNM2 gene in the heterozygous state when these variants affect important protein domains." (PMID 32997713, 2020). "In the human family study, deficiency of CNNM2 has been identified in patients suffering from intellectual disability, seizures, hypomagnesemia, infertility, and altered blood pressure." (PMID 32984406, 2020). "The clinical phenotype with a milder degree of intellectual disability and a later manifestation with hypomagnesemic symptoms during adolescence support a partial loss of CNNM2 function caused by the p.Leu330Phe variant." (PMID 24699222, 2014). "CNNM2 is most highly expressed in the TAL, DCT and brain, which explains the combination of hypomagnesemia with additional neurological symptoms (anatomical abnormalities, seizures and intellectual disability) seen in patients with dominant or sometimes recessive CNNM2 mutations." (PMID 27234911, 2017). "Importantly, patients with recessive CNNM2 mutations suffer from brain malformations and severe intellectual disability." (PMID 24699222, 2014). "Particularly, in patients with a recessive mode of inheritance, the intellectual disability caused by dysfunctional CNNM2 is dramatically severe and is accompanied by severely limited motor skills and brain malformations suggestive of impaired early brain development." (PMID 24699222, 2014). "Furthermore, it can be speculated that neurological phenotypes such as intellectual disability and seizures can be purely caused by CNNM2 variants." (PMID 34490037, 2021). "Strikingly, seizures and intellectual disability are absent in 4 out of 7 cases, indicating these phenotypes are caused either by specific CNNM2 variant only or by additional risk factors." (PMID 38519529, 2024).
Hypertension (9 papers, 2016 to 2025). The presence of chronic increased pressure in the systemic arterial system. "Furthermore, several studies have reported that CNNM2 gene is also associated with schizophrenia, hypertension, intracranial aneurysm, myocardial infarction, pulmonary hypertension, and sleep apnea, among other conditions." (PMID 40612795, 2025). "In addition, CNNM2 has also been implicated in the development of hypertension, intracranial aneurysm, myocardial infarction, pulmonary hypertension, and sleep apnea." (PMID 40612795, 2025). "This is consistent with the single SNP analysis because rs12413409 of CNNM2 was significant in the single SNP-wise EWAS of hypertension." (PMID 34828409, 2021).
diabetes (5 papers, 2017 to 2024). "Genetic variation in CLDN19, CNNM2, FXYD2, SLC41A2, and TRPM6 significantly influenced diabetes risk (p < 0.05), and for CNNM2, FXYD2, SLC41A2 and TRPM6 this risk was completely mediated by serum magnesium levels." (PMID 28224192, 2017). "Genetics seems to be a vital risk factor for Type 2 diabetes, and serum magnesium levels may modify the risk of diabetes through several magnesium-regulating genes such as TRPM6, CLDN19, SLC41A2, CNNM2, and FXYD2." (PMID 35565766, 2022). "Furthermore, common genetic variation in magnesium regulating genes TRPM6, CLDN19, SLC41A2, CNNM2 and FXYD2 significantly modify the risk of diabetes through serum magnesium levels." (PMID 28224192, 2017).